KRAS (KRas proto-oncogene, GTPase)
Diseases named in the same sentence as KRAS in open-access papers (continued):
Sharing a sentence is not in itself a finding about the gene and the disease.
tumor (continued). "Proximal tumours from carriers of the rs76011559 minor allele had similar frequencies of KRAS and BRAF mutations as compared to non-carriers, suggesting that the prognostic effect was independent of somatic mutation status." (PMID 39827162, 2025). "GSEA enrichment analysis indicated that the TLSLow group was enriched in multiple pathways related to immunosuppression and tumor progression, including “HALLMARK KRAS SIGNALING UP”, “HALLMARK HYPOXIA”, “HALLMARK GLYCOLYSIS”, “HALLMARK TGF BETA SIGNALING”, and “HALLMARK NOTCH SIGNALING”." (PMID 40959083, 2025). "In addition, it has also been shown that KRAS is important for maintaining GBM tumor development in vivo." (PMID 40362343, 2025). "KRAS, in turn, leads to the activation of HIF-1a through the mitogen pathways activated by protein kinase or phosphatidylinositol 3 kinase, leading to cell division, metastatic behavior, drug resistance, and tumor recurrence, associated with poor prognosis." (PMID 40149887, 2025). "A KRAS mutation and a CTNNB1 mutation were identified in the tumor." (PMID 39939466, 2025). "Additionally, we investigated the impact of sotorasib administration on FLAG-mEGFP-KRAS activation in tumor tissues, demonstrating a reduction in the proportion of GTP-bound KRAS/G12C to approximately 20%." (PMID 40286847, 2025). "Finally, we used the GEPIA database to determine which of the remaining proteins have an expressional correlation with PRMT5 and KRAS in CRC patient tumor samples." (PMID 40864819, 2025). "We present evidence that STAT3 supports tumor growth following KRAS depletion." (PMID 40859018, 2025). "Analyzing KRAS, NRAS, and BRAF hot-spot mutations at both the nucleotide and protein levels may offer insights into the mutational processes that influence tumor behavior, but functional studies are needed to validate these observations." (PMID 40075837, 2025). "KRAS G12C inhibitors, a promising treatment option, not only inhibit tumor cell proliferation but may also modulate immune cell function by altering the tumor microenvironment." (PMID 40303413, 2025). "TCGA‐derived patient data show that ERK3 is upregulated in tumours regardless of the KRAS (or EGFR) mutation status suggesting complex relationships and multi‐layered roles for ERK3." (PMID 39348153, 2025). "A positive and significant correlation was observed between PD-L1% and HIF-1α% expression in tumor cells, irrespective of KRAS mutation status (Spearman r = 0.321; p = 0.003)." (PMID 39996842, 2025). "Additionally, this combined strategy induced tumor shrinkage in various KRAS-mutant NSCLC xenograft models (G12C, G12S, and Q61H) as well as in various KRAS-mutant NSCLC patients (G12D, G12F, G12S, G12V, and Q61H)." (PMID 40935839, 2025). "Other somatic mutations associated with VTE independent of tumor type include KRAS, STK11, MET, KEAP1, CTNNB1, and CDKN2B." (PMID 39851266, 2025). "Importantly, EVs carry tumour-specific molecules (mutant EGFR, KRAS, PD-L1, oncogenic miRNAs, etc.)that reflect the molecular status of the tumour." (PMID 41311647, 2025). "Evaluating co-occurring mutations depending on PD-L1 status, in PD-L1 negative tumours, KRAS/STK11 mutation was detected in 10% and STK11/KEAP1 mutation in 6% of cases, which was consistent with previous clinical study results." (PMID 40650126, 2025).
tumor (continued). "Following subclustering of only CD8-positive T cells (≈6600 cells) we identified the predicted tumor-specific clonotypes, including the confirmed tumor- and KRAS Q61H-specific clonotypes from patients 2 and 3, in three of the resulting five clusters (clusters 0, 2, and 3)." (PMID 40165973, 2025). "Furthermore, RLY01 enhanced the sensitivity of KRAS-mutant tumor cells to AMG510, thereby overcoming resistance to KRASG12C inhibitors." (PMID 40091835, 2025). "Importantly, SIAIS562055-mediated SOS1 degradation overcame acquired resistance to KRAS inhibitors, leading to tumor regression in mouse xenograft models when combined with KRAS inhibitors." (PMID 39437162, 2025). "Fourth, other important prognostic and biological factors—such as molecular tumor profiles (EGFR, KRAS, ALK mutations), PD-L1 expression, or systemic inflammatory indices beyond NLR/PLR/LMR—were not incorporated into the analysis, potentially limiting mechanistic interpretation." (PMID 41010912, 2025). "In some malignant tumours such as lung adenocarcinoma, RIT1 mutations appear to be mutually exclusive with mutations in currently known driver genes such as KRAS and EGFR, which suggests that RIT1 may be an independent oncogenic factor in some tumours." (PMID 39833023, 2025). "Oncogenic KRAS reprograms cellular metabolism towards aerobic glycolysis, resulting in increased lactate production, which is released into the extracellular space, acidifying the tumor microenvironment." (PMID 38668053, 2024). "Moreover, the oncogenic properties of KRas-G12D were found to rely on the KRAS-PI3Kα interaction, since oncogenesis was significantly inhibited, with tumour cells undergoing apoptosis before the formation of macroscopic tumours." (PMID 39372214, 2024). "However, GSEA (RRID: SCR_003199) revealed differences between the PDX and clinical tumor in some gene sets related to angiogenesis, epithelial–mesenchymal transition and KRAS-up signaling." (PMID 39283723, 2024). "Targeting these myeloid populations for activation through CD40 is an essential and unique step to licensing the tumor immune response during KRAS inhibition, enhances preclinical response to SOS1i+MEKi, and can induce checkpoint blockade–mediated complete response." (PMID 38727236, 2024). "Since only 34 of 52 (65%) patients had sufficient tumor DNA to be used for a BRAF/KRAS mutation analysis, there was no exact evidence to show that there was an association between the mutation status and treatment response." (PMID 38669365, 2024). "Regarding the invasion, there is an absence of significant associations between KRAS mutations and tumor stage (p-value = 0.213) as well as T invasion depth (p-value = 0.52)." (PMID 38465160, 2024).
tumor (continued). "Among these genes are ERBB2, CCNA1, FOXC2, LEFTY2, VTN, ACKR3, and PTGS2, which influence processes such as apoptosis, epithelial–mesenchymal transition, angiogenesis, hypoxia responses, and KRAS signaling pathways, all vital for tumor aggressiveness and metastatic spread." (PMID 39000413, 2024). "The tumor was microsatellite stable (MSS) and harbored a KRAS G12C mutation (NRAS/BRAF wild type)." (PMID 38539256, 2024). "Inhibiting transcription in cancers with aberrant KRAS expression has proven to be detrimental to tumor cells, revealing their dependency on KRAS independent of its mutational status and provides a wide scope for therapeutic intervention." (PMID 39457457, 2024). "KRAS or NRAS were mutated in six tumours (16%), and IDH1 or IDH2 were mutated in 5 tumours (14%)." (PMID 38877653, 2024). "In CRC patients co-treated with KRASi and EGFRi, low-frequency non-G12C KRAS mutations were detected in circulating tumor DNA, but were not well maintained over time." (PMID 38668053, 2024). "Additionally, attention was given to detecting the mutant status of KRAS using techniques such as liquid biopsy, next-generation sequencing, and circulating tumor DNA." (PMID 38706597, 2024). "Hence, KRAS-G12C mutant cells treated with the covalent inhibitor ARS1620, which forms semi-antigenic MHC-I complexes, can be utilized as tumor-specific new antigens to evoke CTL responses against KRAS-G12C cells, thereby enhancing therapeutic efficacy." (PMID 39802954, 2024). "Hence, the relationship between oncogenic KRAS and tumor immunogenicity is of interest, particularly as selective KRAS inhibitors have now entered the clinical arena." (PMID 39113608, 2024). "However, the mechanism by which oncogenic KRAS coordinates metabolic reprogramming to promote tumor growth remains an area of intense investigation." (PMID 38886847, 2024). "KRAS mutations are very common in CRC (45% of cases) and help drive tumor growth [1377]." (PMID 39273409, 2024). "While the enrollment criteria required patients to have RAS WT tumor tissue based on local assessment using a validated test, a small proportion of patients was found to have RAS mutations (6.0% with KRAS and 1.4% with NRAS mutations) according to the ctDNA test." (PMID 38347302, 2024). "Furthermore, Myc depletion led to increased expression of IFN signaling molecules, which were not further upregulated upon treatment with MEKi, suggesting that oncogenic KRAS suppresses tumor-intrinsic IFN responses by driving expression of Myc." (PMID 38635884, 2024). "It was discovered that the expression of PEDF, which is a PDA tumor suppressor, decreases in the transforming epithelium not strictly due to the KRAS mutation, but under the influence of macrophages." (PMID 39457573, 2024). "We assessed KRAS expression in all 17 samples with sufficient tumor cell infiltrates." (PMID 39513319, 2024). "The prevalence of KRAS mutation was not significantly different between HRASmt and HRASwt tumors across all investigated tumor types." (PMID 38672653, 2024). "Furthermore, in KRAS-mutated NSCLC, DRP1 has been shown to provide energy for tumor cell growth by utilizing lactate and preventing ROS-induced oxidative clearance, thereby promoting cell proliferation." (PMID 39430236, 2024). "This interplay could further enhance EMT, facilitating tumor progression and resistance to KRAS-targeted therapies." (PMID 39061234, 2024).
tumor (continued). "Given that KRAS can be indirectly regulated by miRNAs through the genes interacting with KRAS, it is crucial to highlight the potentially pivotal role of miRNAs in tumour promotion in PC and other cancers through complex regulatory networks." (PMID 39057123, 2024). "GS3, a KRAS‐activated subtype, is characterized by high tumor purity and immune‐desert." (PMID 38332637, 2024). "We showed that pCASTOR1 scores were significantly higher in tumor cells than non-tumor cells irrespective of the presence of KRAS or EGFR mutations in tumor cells." (PMID 39385301, 2024). "KRAS or MET mutations were also associated with higher TMB, indicating that mutations in these genes may promote tumor immunogenicity in NSCLC." (PMID 38394518, 2024). "In addition, KRAS mutant promotes metabolic reprogramming, which generates nutrients necessary to maintain unrestricted proliferation of tumor cells." (PMID 38954030, 2024). "In the last step of KRAS landing on the plasma membrane, perturbing KRAS/PDE-δ could be a tractable therapeutic strategy in restricting the tumor neoplastic growth and downstream effector pathways." (PMID 39056802, 2024). "It’s important to consider, however, that elevated VAFs could also be indicative of genome duplication events or an increase in KRAS dosage, both of which are known to contribute to the aggressive behavior of tumor biology." (PMID 38619751, 2024). "KRAS is involved in promoting cancer progression by reducing tumor immunogenicity." (PMID 39199659, 2024). "Mutant KRAS (KRASMUT) is often exploited by cancers to shape tumor immunity, but the underlying mechanisms are not fully understood." (PMID 38216551, 2024). "Conversely, KRAS (p = 2.67e−90), FBXW7 (p = 1.29e−14), BRAF (p = 9.32e−8), GNAS (p = 2.54e−29), and SMAD2 (p = 3.93e−5) mutated tumors were significantly more common in MSLN high expressing tumor samples versus MSLN low expressing tumor samples." (PMID 39174744, 2024). "Specifically, the KRAS-G12V mutation generates a 9-peptide neoantigen that can be effectively recognized by specific TCRs, triggering the activation of TCR-T cells to secrete cytokines and kill tumor cells." (PMID 39439803, 2024). "The combination of the FAK-inhibitor defactinib with the dual RAF/MEK inhibitor avutometinib (VS-6766) may overcome this resistance and has shown synergistic antitumor activity in KRAS wild-type LGSOC patient-derived tumor xenografts." (PMID 39409889, 2024). "For the first time, an association between components of the KRAS/ATR/CHEK1-signaling pathway, responsible for coordinating replicative stress, and markers of tumor progression, including invasiveness and tumor recurrence, has been established in patients with stage I ECE." (PMID 38669256, 2024). "Additionally, low expression of the KRAS signaling downregulation pathway, indicated by the reverse pathway analysis, hints at abnormal activation of the KRAS pathway in these tumor samples." (PMID 39592929, 2024). "Mutational exclusivity between KRAS and B-RAF mutations can cause variations in the immune response to tumours, with KRAS-mutant tumours exhibiting a lower rate of immune cell infiltration compared to WT, whereas B-RAF mutations caused an increase in immune cell infiltration, compared to WT." (PMID 39372214, 2024).
tumor (continued). "Hence, our findings also warrant careful laboratory exploration to more conclusively link KRAS/STK11 mutations, lipid metabolism, and tumor immunity." (PMID 39113608, 2024). "Furthermore, FMC-376, a novel dual KRAS G12C (ON) and (OFF) inhibitor, has shown anti-tumor activity in vivo, suggesting the ability to overcome the resistance to KRAS G12C (OFF) inhibitors." (PMID 38756650, 2024). "The results of high‐throughput RNA sequencing showed that the regulatory effect of TOX3 on the malignant biological behavior of HCC cells involved mainly focused on signaling pathways related to tumor growth and metastasis, such as the KRAS, MAPK, and EMT pathways." (PMID 38463397, 2024). "There is also evidence that increased mutated KRAS levels in circulating tumour DNA also have a negative prognostic significance." (PMID 38953007, 2024). "This protein inhibited the proliferation of KRAS-mutant tumor cells." (PMID 39125664, 2024). "Moreover, KRAS expression is changed both in the very center of the tumor as well as in the adjacent-to-the-tumor area, and in other IPMNs." (PMID 39594780, 2024). "Notably, recent research has notably highlighted the upregulation of the Y chromosome gene KDM5D in KRAS-mutated CRC, which influences tumor cell adhesion and immune responses through the KRAS-STAT4 signaling pathway." (PMID 39731171, 2024). "In our study, two patients had repeat tumor biopsies with discordant KRAS G12C results." (PMID 39195317, 2024). "Furthermore, GSEV result spot that tumor promotive signal such KRAS, EMT and IL-6/JAK/STAT3 are restricted under anoikis-related condition." (PMID 39568815, 2024). "KRAS activation stimulates downstream signaling cascades and drives tumor progression." (PMID 38908072, 2024). "Together, these results demonstrate key differences in how RAS wild-type normal tissues react and adapt to metronomic RAS inhibition with a broad-spectrum RAS inhibitor compared with tumours driven by mutant KRAS, providing a rational basis for the tumour selectivity of RAS inhibition in PDAC." (PMID 38588697, 2024). "Three of the samples show frequencies of greater than 50%, which suggests that copy number amplification of the KRAS locus has occurred in these samples and that simply doubling the KRAS frequency will overestimate the tumor’s cellularity—a limitation of this approach." (PMID 39123450, 2024). "Thus, is it possible that mutant (i.e. KRAS) tumor cells confer cetuximab resistance to WT tumor cells through paracrine signaling, perhaps in the form of AREG-containing EVs." (PMID 40727266, 2024). "KRAS inhibitor response may critically depend on a sustained inhibition of KRAS-pathway function and sensitivity of KRASmut tumor cells to alternative bypass pathway mechanisms." (PMID 38191673, 2024). "Given the known role of oncogenic KRAS in mediating immune evasion, we next wanted to understand whether tumor-intrinsic COX2 expression was regulated by KRAS signaling." (PMID 38635884, 2024). "Additionally, further validation of KRAS and BRAF V600E mutations in these tumours requires larger-scale sequencing data." (PMID 39484039, 2024). "Additionally, our study demonstrated that deferasirox, an oral iron chelator, significantly diminishes cell viability and tumor growth in KRAS-mutant PDAC by targeting FTH1-mediated pathways and altering the PYCR1/PRODH expression ratio." (PMID 39294443, 2024). "Moreover, simultaneous blockade of the complement system and CDK9 significantly impeded immune evasion and retarded tumor growth in KRAS‐mutant xenografts." (PMID 39254172, 2024).